ZNF587B (zinc finger protein 587B)
Description:
May be involved in transcriptional regulation.
Tractability: PROTAC: UniProt records ubiquitination sites on it; ubiquitination databases record sites on it.
Gene: Protein-coding gene on chromosome 19 (57,819,721 to 57,846,238, forward strand). Ensembl gene ENSG00000269343.
Subcellular location: Nucleus
Subcellular location (Human Protein Atlas): Nucleoplasm
Gene Ontology:
Molecular function: DNA-binding transcription factor activity, RNA polymerase II-specific; RNA polymerase II transcription regulatory region sequence-specific DNA binding
Biological process: regulation of transcription by RNA polymerase II; regulation of DNA-templated transcription
Cellular component: nucleus
Genetic constraint (gnomAD): Loss-of-function variants: 6 observed, 6.64 expected, observed/expected ratio (o/e) 0.9, 90% interval 0.49 to 1.69. That is too few expected variants to judge how well the gene tolerates losing a copy. Missense variants: 749 observed, 751.6 expected, observed/expected ratio (o/e) 1, 90% interval 0.94 to 1.06. Synonymous variants: 274 observed, 252.48 expected, observed/expected ratio (o/e) 1.09, 90% interval 0.98 to 1.2.
Homologues: Orthologues: mouse Zfy1 (18% identical), tropical clawed frog zfx (18% identical), mouse Zfy2 (17% identical), rat Zfy1 (17% identical), zebrafish zfx (17% identical). Paralogues in human: ZNF418 (61% identical), ZNF552 (56% identical), ZNF551 (47% identical), ZNF256 (45% identical), ZNF304 (45% identical), ZNF792 (41% identical), ZNF549 (39% identical), ZNF548 (38% identical), ZNF772 (36% identical), ZIK1 (35% identical), ZNF586 (34% identical), ZNF419 (33% identical), and 26 more.
Diseases named in the same sentence as ZNF587B in open-access papers:
ZNF587B is named in the same sentence as 3 diseases in open-access papers, as found by Europe PMC text mining. Sharing a sentence is not in itself a finding about the gene and the disease. The quoted sentences say what the papers report.
ovarian carcinoma (2 papers, 2022 to 2025). A malignant neoplasm originating from the surface ovarian epithelium. "In a similar study with the GeCKO library in the A2780 and SKOV3 ovarian cancer cell lines, ZNF587B, TADA1, SEMA4G, POTEC and USP17L20 were identified as candidate genes; among these, loss of ZNF587B and SULF1 gene expressions were associated with cisplatin resistance." (PMID 40242936, 2025). "ZNF587B is also an important transcription factor that has been found to be related to ovarian cancer and may be a therapeutic target." (PMID 35051904, 2022).
cancer (1 paper, 2024). A tumor composed of atypical neoplastic, often pleomorphic cells that invade other tissues. "Recently, in a study about A>I(G) RNA editing across all available cancer cell lines, only two RNA-edited sites, Chr19:58355670 (A/G) in ZNF587B and Chr20:36147563 (T/C) in BLCAP, were associated with sensitivity to doxorubicin specifically in BC cell lines." (PMID 38672084, 2024).
neurodegenerative disease (1 paper, 2024). A disorder of the central nervous system characterized by gradual and progressive loss of neural tissue and neurologic function. "Our results found AQR, ZNF587B, CRP, and PAGIn have been accumulated in AD patients as well as been reported associated with neurodegenerative diseases, while their relationship with AD has not been thoroughly examined." (PMID 38605603, 2024).